ITGB1 (integrin subunit beta 1)
Diseases named in the same sentence as ITGB1 in open-access papers (continued):
Sharing a sentence is not in itself a finding about the gene and the disease.
pneumonia (2 papers, 2020 to 2022). An acute, acute and chronic, or chronic inflammation focally or diffusely affecting the lung parenchyma, caused by an infection in one or both of the lungs (by bacteria, viruses, fungi, or mycoplasma.). "Results suggested that 5 proteins with greater node degrees [i.e. catenin beta-1 (CTNNB1), integrin beta-1 (ITGB1), catenin alpha-1 (CTNNA1), dynamin-2 (DNM2), Keratin, type I cytoskeletal 19 (KRT19)] might function as crucial players in pneumonia-related bacterial infection in FMD." (PMID 36387401, 2022).
renal carcinoma (2 papers, 2019 to 2024). A carcinoma arising from the epithelium of the renal parenchyma or the renal pelvis. "In renal cancer (RC), TG2 lessens ITGB1 adhesion to promote renal cancer cell invasion." (PMID 38279122, 2024).
renal failure (2 papers, 2018 to 2021). "Suppression of Itgb1 in Pax8 expressing cells impairs glomerular and tubular function leading to progressive renal failure." (PMID 30271355, 2018). "Itgb1f/f-Pax8cre/+ mice develop overt proteinuria and severe renal failure at the same extent as showed in podocytes specific Itgb1 cKO mice." (PMID 30271355, 2018). "Itgb1-Pax8 cKO mice develop a progressively worsening proteinuria and renal abnormalities leading to severe renal failure and hypertension." (PMID 30271355, 2018).
schizophrenia (2 papers, 2015 to 2019). A major psychotic disorder characterized by abnormalities in the perception or expression of reality. "There were several studies showing that ITGB1 gene has a possible role during the development of schizophrenia." (PMID 31598692, 2019).
silicosis (2 papers, 2024 to 2025). Silicosis is a respiratory disease caused by breathing in (inhaling) silica dust. "The silicosis rat model group expressed ITGB1 at much higher levels than the saline control group." (PMID 39258668, 2024). "However, it remains to be determined whether ITGB1 also interacts with other signaling pathways to influence the onset and progression of silicosis." (PMID 39258668, 2024). "Therefore, ITGB1 can be used as a potential target for the treatment of silicosis." (PMID 39258668, 2024). "CRISPR/Cas9 technology to knockdown ITGB1 can inhibit the integrin/ILK signaling pathway and alleviate silicosis fibrosis, offering a fresh perspective on silicosis therapy." (PMID 39258668, 2024). "However, the function of ITGB1 in silicosis remains unclear." (PMID 39258668, 2024). "Therefore, in this study, we assessed the relationship between ITGB1 and EMT and the role of ITGB1 in silicosis fibrosis." (PMID 39258668, 2024).
tendinopathy (2 papers, 2011 to 2023). "Also, upregulation of genes encoding proteoglycans (BGN) glycoproteins (TNC, FN1, SPARC), integrins (ITGB1), and growth factors has been reported in tendinopathy patients." (PMID 38001919, 2023).
thyroid tumor (2 papers, 2023 to 2024). A benign or malignant neoplasm affecting the thyroid gland. "Furthermore, the in vivo tumorigenic assays revealed that the overexpression of PLA2R1 could inhibit the growth and proliferation of the thyroid tumor by modulating the ITGB1/FAK-signaling axis, compared to the control group in the animal study." (PMID 37345058, 2023).
acute lung injury (1 paper, 2024). A condition of lung damage that is characterized by bilateral pulmonary infiltrates (pulmonary edema) rich in neutrophils, and in the absence of clinical heart failure. "Integrins play an important role in regulating vascular permeability; in particular, Itgb1 and Itgb4 have been shown to protect from vascular leakage in acute lung injury." (PMID 39513364, 2024).
adenomyosis (1 paper, 2021). The growth of endometrial tissue inside the muscular wall of the uterine corpus. "In the present study, we found that integrin subunit α1 (ITGA1) and integrin subunit β1 (ITGB1) were decreased in adenomyosis group, while were elevated in Anti-NGF group, which might be beneficial for the embryo implantation." (PMID 32676925, 2021). "The expression levels of ITGA1, ITGB1, LAMC1, and CKM are downregulated in the adenomyosis group compared with those in control group, while those proteins are successfully recovered by anti-NGF treatment." (PMID 32676925, 2021). "Western blotting confirmed that the expression levels of integrin alpha-1 (ITGA1), integrin beta-1 (ITGB1), laminin subunit gamma-1 (LAMC1), and creatine kinase M-type (CKM) were decreased in adenomyosis group, whereas those levels were elevated after anti-NGF treatment." (PMID 32676925, 2021). "Furthermore, ITGB1, ITGA1, LAMC1, and CKM might participate in the recovery of adenomyosis." (PMID 32676925, 2021).
age (1 paper, 2025). A temporal measurement of the time period elapsed since an identifiable point in the life cycle of an organism. "The comprehensive results show that decorin plays a sarcoprotective role by activating the ITGB1/Akt/mTOR pathway and may serve as a potential therapeutic reagent in age‐associated sarcopenia." (PMID 41350105, 2025).
amyotrophic lateral sclerosis (1 paper, 2024). Amyotrophic lateral sclerosis (ALS) is a neurodegenerative disease characterized by progressive muscular paralysis reflecting degeneration of motor neurons in the primary motor cortex, corticospinal tracts, brainstem and spinal cord. "KEGG pathway analysis from downregulated DEmiRs after ITGB1 depletion showed enrichment in Glycosphingolipid biosynthesis-globo and isoglobo series, Amyotrophic lateral sclerosis (ALS) and Hippo signaling pathway-multiple species." (PMID 38767703, 2024).
Atrophy (1 paper, 2025). Any weakening or degeneration, especially through lack of use. "In this study, we detected a decrease in the expression of the ITGB1/FAK/AKT pathway in DRGs of diabetic rats compared to normal rats, which may provide a breakthrough in the study of demyelination or axonal atrophy in diabetic neuropathy." (PMID 41031221, 2025).
Autoimmunity (1 paper, 2022). The occurrence of an immune reaction against the organism's own cells or tissues. "Our data suggest that a subset of innate B-1 cells, identified by classical markers (Bhlhe41, Cd43, and IgM) and context-specific markers (Cxcr3 and Itgb1), can contribute to autoimmunity in BOS, and thus represent potential therapeutic value." (PMID 36134664, 2022).
benign skin tumors (1 paper, 2025). "Mutations in ITGB1 have been shown to convert benign skin tumors into malignant ones." (PMID 40362482, 2025).
carcinoid (1 paper, 2021). "The expression of COL1A2, COL3A1, COL5A2, ITGA5, and ITGB1 in SCLC, LCNEC, and typical carcinoid samples in the GSE1037 profile, as compared with normal samples, were determined using a GEO2R online analyzer (log FC>2 and adjusted P<0.05) and then compared to the data from our cohort." (PMID 34458147, 2021).
cataract (1 paper, 2022). Partial or complete opacity of the crystalline lens of one or both eyes that decreases visual acuity and eventually results in blindness. "ITGB1 and SPARC exhibit lens epithelial cell-like characteristics in cataracts." (PMID 35721704, 2022).
chondrodysplasia (1 paper, 2013). "A targeted inactivation of the ITGB1 gene in murine cartilage, and the subsequent loss of all β1-integrins, has been shown to result in frequent perinatal lethality and severe chondrodysplasia with markedly abnormal growth plate morphology." (PMID 24086591, 2013).
chronic myeloid leukemia (1 paper, 2023). "The top five most activated Kyoto Encyclopedia of Genes and Genomes (KEGG) terms involving ITGB1 were insulin signaling pathway, ERBB signaling pathway, regulation of actin cytoskeleton, chronic myeloid leukemia, and neurotrophin signaling pathway." (PMID 37449209, 2023).
Cognitive impairment (1 paper, 2023). Abnormal cognition is characterized by deficits in thinking, reasoning, or remembering. "Furthermore, recent investigations have demonstrated that hsa-mir-106a-5p which based on our results is linked to (TGFB1, ITGB1, and CXCR4), reduces the level of VEGFA, a protective factor against cognitive impairment in AD patients." (PMID 37705610, 2023).
colorectal adenocarcinoma (1 paper, 2020). The most common type of colorectal carcinoma. "Moreover, the expression of β1-integrin protein was significantly higher in colorectal adenocarcinomas tissue samples of stage III than those in stage I-II, indicating that the expression level of ITGB1 might be associated with the stage of disease." (PMID 33014056, 2020).
cystic fibrosis (1 paper, 2022). Autosomal recessive disorder caused by pathogenic variants in the CFTR gene (cystic fibrosis transmembrane conductance regulator), which encodes a chloride and bicarbonate channel expressed in epithelial cells, and follow the diagnosis criteria. "ITGB1, also named β1-integrin, hindered bacterial clearance and facilitated bacterial infection in cystic fibrosis airway cells and cystic fibrosis mice." (PMID 36387401, 2022).
diabetic nephropathy (1 paper, 2022). "On the other hand, altered density or activity of integrin molecules such as integrin β1 (ITGB1) have been implicated in a variety of diabetic complications, particularly diabetic nephropathy." (PMID 35628588, 2022).
dry eye (1 paper, 2023). "ITGB1 and especially ITGB8 are down-regulated in patients with dry eye." (PMID 38254630, 2023).
endothelial dysfunction (1 paper, 2024). In vascular diseases, endothelial dysfunction is a systemic pathological state of the endothelium (the inner lining of blood vessels) and can be broadly defined as an imbalance between vasodilating and vasoconstricting substances produced by (or acting on) the endothelium. "Thus, elevated macrophages–ECs and cholangioctes–ECs interactions via Nampt-Insr and Nampt-Itga5/Itgb1 were found in CHB mice livers, indicating the role of VISFATIN/Nampt- NF-κB axis in endothelial dysfunction and the Insr/Itga5-VEGF axis in angiogenesis." (PMID 39000126, 2024).
ependymoma (1 paper, 2023). A WHO grade II, slow growing tumor of children and young adults, usually located intraventricularly. "Gene expression analysis indicates that transcription of integrin β4 (ITGB4), but not β1 (ITGB1), is significantly up-regulated in PFA compared to ZFTA ependymoma and normal brain samples, suggesting that the integrin α6β4 heterodimer is the functional form relevant for PFA tumors." (PMID 37085539, 2023).
epilepsy (1 paper, 2013). A brain disorder characterized by episodes of abnormally increased neuronal discharge resulting in transient episodes of sensory or motor neurological dysfunction, or psychic dysfunction. "Down-regulation of adhesion molecules, including integrin (ITGB1, ITGB2) and cadherin family members (CDH11) in the peritumoral tissue of the subjects with epilepsy also serve to validate our study, as they have also been found to contribute to the cell biology underlying epileptogeneis." (PMID 23418513, 2013).
esophageal adenocarcinoma (1 paper, 2022). A malignant tumor with glandular differentiation arising predominantly from Barrett mucosa in the lower third of the esophagus. "The aim of this study was to analyze the expression of ITGB1 in esophageal adenocarcinoma and possibly correlate the expression profile with clinico-pathological, molecular and survival data." (PMID 36456612, 2022). "To date, there is no analysis of ITGB1 expression in esophageal adenocarcinoma." (PMID 36456612, 2022). "To date, the impact of ITGB1 on survival in esophageal adenocarcinoma has not been studied." (PMID 36456612, 2022).
Gliosis (1 paper, 2021). Gliosis is the focal proliferation of glial cells in the central nervous system. "However, in contrast to the observed downregulation of ITGB1, GFAP and vimentin, two prototype markers of gliosis, were not changed by modifying glucose levels in RMG." (PMID 34046254, 2021).
Glucose intolerance (1 paper, 2022). Glucose intolerance (GI) can be defined as dysglycemia that comprises both prediabetes and diabetes. "In two studies from the Wang lab on mice with beta cell specific loss of Itgb1, it was initially shown that the male mutant mice have normal fasting glucose levels but glucose intolerance, while female mutants are normal in fasting glucose and glucose tolerance." (PMID 35835371, 2022).
Granuloma (1 paper, 2022). A compact, organized collection of mature mononuclear phagocytes, which may be but is not necessarily accompanied by accessory features such as necrosis. "The most abundant subcluster (8.3% of granuloma cells, q = 0.074, Dirichlet p = 0.00049) exhibited elevated expression of markers of naive and memory T cells (TCF7, CCR7, IL7R, and TXNIP) and activation or memory state (CD69 and ITGB1)." (PMID 35483355, 2022).
HCMV infection (1 paper, 2018). "Acetylation could inhibit ITGB1 ubiquitin-mediated degradation and support HCMV infection." (PMID 30470744, 2018).
hemorrhagic stroke (1 paper, 2021). A stroke caused by a bleed on the brain. "The alteration of ITGB1 and ITGB3 expression in cerebral tissue of rats with hemorrhagic stroke was detected by WB." (PMID 33641668, 2021).
HIV-1 infection (1 paper, 2021). The type species of lentivirus and the etiologic agent of acquired immunodeficiency syndrome (AIDS). "Interestingly, FAM120AOS was suggested to be able to regulate the expression of ITGB1 (CD29), whereas ITGB1 has already been reported to be correlated with HIV-1 infection." (PMID 35004856, 2021).
Hypercholesterolemia (1 paper, 2023). An increased concentration of cholesterol in the blood. "The observed downregulation of integrins, integrin-related proteins (ITGB1 and ILK) and TGF-β in the presence of oxLDL may impair the normal adaptive response to exercise in individuals with hypercholesterolemia." (PMID 36927534, 2023).
Hypertension (1 paper, 2018). The presence of chronic increased pressure in the systemic arterial system. "We showed here that the suppression of Itgb1 in renal epithelial cells leads to a general impairment of renal function including an increasingly worsening proteinuria and urinary concentrating defect, ending up to severely low GFR and hypertension." (PMID 30271355, 2018).
incontinence (1 paper, 2025). "Integrins have a well-established function in mechanotransduction, and conditional urothelial Itgb1 KO mice exhibit elevated mucosal ATP release (serosal release was not determined), as well as bladder overactivity and incontinence when assessed in void-spot studies." (PMID 41348674, 2025).
injury (1 paper, 2023). Damage inflicted on the body as the direct or indirect result of an external force, with or without disruption of structural continuity. "We also monitored the roles of ITGB1‐deleted TCs in the cytokine production, mitochondrial function, and intracellular signaling pathways of MSCs, as well as therapeutic effects in experimental acute lung injury after co‐transplantation of MSCs with TCs or ITGB1‐delated TCs." (PMID 37855260, 2023).
iris coloboma (1 paper, 2016). "Interestingly, Crim1null and Itgb1flox compound heterozygotes displayed iris coloboma and cataract, confirming that Crim1 and Itgb1 genetically interact." (PMID 26681494, 2016).
ischemic stroke (1 paper, 2025). A stroke disorder caused by obstruction of blood flow to the brain, due to thrombotic (local blood clot formation) or embolic (due to a blood clot or other material traveling from another site) event. "Because ANGPT2 regulates angiogenesis through TEK and integrin signaling, and promotes neuroprotection in a model of ischemic stroke, the ANGPT2–TEK/ITGA5:ITGB1 signaling axis from EC:Exc3/Exc5 to fibroblasts (EC:Fib) likely represents a resilience-linked angiogenic support mechanism." (PMID 41035073, 2025).
kidney cancer (1 paper, 2018). Primary or metastatic malignant neoplasm involving the kidney. "Our study identified that the expression of CD151 downstream genes ITGB1, ITGB4, and PLEC may have additional prognostic values in kidney cancers." (PMID 29843367, 2018).
leishmaniasis (1 paper, 2025). Infectious disease that is transmitted through the bite of hematophagous female phlebotomine sand flies. "Although the potential of SAA1/2 and ITGB1 as biomarkers has been described in other systemic diseases, this study highlights their significance specifically in the context of leishmaniasis." (PMID 41019078, 2025).
Lissencephaly (1 paper, 2016). A spectrum of malformations of cortical development caused by insufficient neuronal migration that subsumes the terms agyria, pachygyria and subcortical band heterotopia. "The overmigration of neurons through the BM that was visible as a cobblestone lissencephaly in the C3GEmx1-KO resembles the phenotype of cortex-specific Ptk2 (encoding FAK) and Itgb1 (β1 integrin) knockouts." (PMID 27111087, 2016).
metastatic prostate carcinoma (1 paper, 2021). A carcinoma that arises from the prostate gland and has spread to other anatomic sites. "Among the eight integrin subunits analyzed, ITGA5, ITGAV, ITGB1, ITGB3, ITGB4, and ITGB5 were upregulated in the bone compared with the other organs, suggesting that some integrins may confer osteotropic properties on metastatic prostate cancer." (PMID 33514011, 2021).
microphthalmia (1 paper, 2016). Congenital or developmental anomaly in which the eyeballs are abnormally small. "Although knockout of the mouse β1 integrin gene (Itgb1) leads to peri-implantation lethality, conditional knockout of Itgb1 in lens results in cataract and microphthalmia due to apoptosis of LE cells and loss of the LE cell phenotype." (PMID 26681494, 2016).
migraine (1 paper, 2025). "In this study, we identified that NTG-induced migraine is associated with the PI3K–Akt signaling pathway, cytokines and their receptor interactions, and nine key hub genes (Alb, Tgfb1, Cd4, Ptprc, Itgb1, Icam1, Col1a1, Pxdn, and Itgad) through transcriptomics." (PMID 40699640, 2025). "Although current evidence does not directly link Itgb1, Itgad, Col1a1, and Pxdn to migraine, their functional relevance in inflammation and vascular remodeling suggests that they may contribute to migraine pathogenesis." (PMID 40699640, 2025).
nervous system cancer (1 paper, 2017). A primary or metastatic malignant neoplasm involving the nervous system. "Previously, there were 24 studies indicated that ITGB1 was a potential cancer driver in the Candidate Cancer Gene Database (CCGD), involved in liver, colorectal, pancreatic and nervous system cancer." (PMID 28537888, 2017).
neuropathy (1 paper, 2025). A disorder affecting the nervous system that manifests with pain, tingling, numbness, and/or muscle weakness. "It has been shown, for example, that Schwann cells of ITGB1-null mice do not form normal processes around axons, and these animals develop severe neuropathy." (PMID 41300342, 2025).
preeclampsia (1 paper, 2016). Preeclampsia is a hypertensive disorder of pregnancy that is characterized by new-onset hypertension with proteinuria presenting after 20 weeks of gestation, and depending on mild or severe forms may initially present with severe headache, visual disturbances, and hyperreflexia. "Previous studies have shown that ITGB1 expression is identical in normal placental tissue, in miscarriages, and in pregnancies complicated by preeclampsia." (PMID 27556547, 2016).
progeria (1 paper, 2020). "Furthermore, Cdon and Itgb1* levels were either decreased or mislocalized in satellite cells on myofibers isolated from Zmpste24−/− mice, a model of progeria." (PMID 32103583, 2020).
pulmonary neuroendocrine neoplasms (1 paper, 2023). "In a recent study, the up-regulation of six fibrogenic genes (COL5A2, COL1A2, COL3A1, ITGA5, ITGB1, and ITGB1) in pulmonary neuroendocrine carcinoma and the down-regulation of pulmonary neuroendocrine neoplasms were strongly related to no metastasis and overall survival." (PMID 37047300, 2023).
rectal cancer (1 paper, 2024). A primary or metastatic malignant neoplasm that affects the rectum. "CXCL10, IL12A, CD247 and ITGB1 were identified as predictive markers for the response to neoadjuvant treatment in rectal cancer in previous studies." (PMID 38406803, 2024).